BRCA2 (BRCA2 DNA repair associated)
Diseases named in the same sentence as BRCA2 in open-access papers (continued):
Sharing a sentence is not in itself a finding about the gene and the disease.
breast cancer (continued). "Furthermore, understanding how autophagy is influenced in different BRCA gene variants and HR-deficient tumors, as well as how Dox affects autophagy in BRCA2-mutated patients, is pivotal for refining breast cancer treatment strategies." (PMID 39199310, 2024). "The first hypothesis is that 4% to 40% of male breast cancer patients harbor a BRCA2 germline mutation." (PMID 38717807, 2024). "BRCA1 mutations appear in 50–80% and BRCA2 mutations in 40–70% of breast cancer risks." (PMID 38791944, 2024). "Missense mutations of BRCA2 can moderately increase the risk for breast cancer, but it is unknown if they also modulate the response to PARP inhibitors." (PMID 38664720, 2024). "Furthermore, discovering pathogenic variants in BRCA1 DNA repair associated (BRCA1) and BRCA2 genes has been pivotal to our understanding of both hereditary and sporadic breast cancers." (PMID 39484719, 2024). "In addition, both BRCA1 and BRCA2 mutations predispose to a breast cancer lifetime risk of greater than 60%." (PMID 38256099, 2024). "Mutations in BRCA1 and BRCA2 are observed in approximately 25% of breast cancer cases." (PMID 38927753, 2024). "Also, the well-known genes BRCA1 and BRCA2 that predispose to breast cancer are considered to be part of the FANC gene family." (PMID 39051418, 2024). "Additionally, 13 polymorphisms (4 in BRCA1 and 9 in BRCA2) were identified, of which 2 are associated with a moderate increase in breast cancer risk (BRCA2 c.1114A>C and c.875566T>C)." (PMID 39338246, 2024). "Patients with BRCA1 mutations in breast cancer benefit more from platinum-based protocols than patients with BRCA2 mutations, suggesting that patients with BRCA1 mutations may be more sensitive to platinum-based drug therapy." (PMID 40231011, 2024). "Similarly, we found a significant increase in R-loops (~1.5- to 2-fold increase) upon Mlh1 knockdown in BRCA2-deficient mouse mammary tumor cell line KB2P1.21." (PMID 38271119, 2024). "In a meta-analysis that included 13,965 BRCA1 and 7,057 BRCA2 mutation carriers enrolled on 14 observational studies, the breast cancer risk among BRCA1 mutation carriers was lowered by RRSO (HR = 0.63, 95% CI, 0.49-0.81, P < 0.01) and BRCA2 mutation carriers (HR= 0.51, 95% CI, 0.34-0.75, P < 0.01)." (PMID 39507757, 2024). "Furthermore, BSO has been linked to a lowered risk of breast cancer, particularly in pre-menopausal women with BRCA2 mutations." (PMID 39594243, 2024). "BRCA1 and BRCA2 pathogenic variant carriers develop breast cancers with distinct pathological characteristics and mutational signatures that may result in differential response to chemotherapy." (PMID 39060255, 2024). "Clinical and pathologic characteristics for patients with BRCA1 and BRCA2 were compared, and estimates of overall survival, bilateral mastectomy-free survival, distant disease-free survival, risk of ipsilateral breast cancer, and risk of contralateral cancer were computed." (PMID 38916888, 2024). "BRCA2 is primarily associated with breast cancer and less frequently with ovarian cancer." (PMID 38711004, 2024). "Pathogenic and likely pathogenic germline variants in the BRCA1 and BRCA2 genes play a pivotal role in breast cancer development and progression and can determine the optimal risk-reducing strategies and personalized case management for the carriers of such variants." (PMID 39796670, 2024). "In addition, mutations in genes such as BRCA1 and BRCA2 can significantly increase the risk of developing breast cancer." (PMID 39795956, 2024). "Additionally, young women who develop breast cancer under the age of 40 (YWBC) harbor deleterious germline mutations in BRCA1 (gBRCA1m) or BRCA2 (gBRCA2m) in approximately 12% of cases." (PMID 38398129, 2024).
breast cancer (continued). "In this report, we present the case of a female BRCA2 mutation carrier who was diagnosed with five different malignancies: two independent breast cancers, well-differentiated liposarcoma, clear cell renal cell carcinoma (ccRCC) and therapy-related myeloproliferative neoplasia." (PMID 39702187, 2024). "Breast cancer risks in older BRCA2 pathogenic variant carriers are understudied." (PMID 39072245, 2024). "The expression of mesenchymal-like features resulting from complete or partial EMT can cause increased resistance to chemotherapeutic and targeted agents, therefore driving acquired resistance such as in the case of PARP inhibitor resistance in models of BRCA2-mutated mammary tumors." (PMID 38010394, 2024). "However, rs11571833 and rs17879961 are located on well-established breast cancer susceptibility genes BRCA2 and CHECK2 respectively." (PMID 38817965, 2024). "Carriers of the BRCA1 or BRCA2 genetic mutation have an 80 to 85% risk of developing breast cancer." (PMID 39335183, 2024). "In conclusion, although previous researchers have reported cases of individuals with BRCA2 mutations who developed both breast cancer and prostate cancer simultaneously, this is the first documented case of a family with a history of breast cancer who also developed prostate cancer." (PMID 39364320, 2024). "Genetic testing could be offered to women with a familial history of breast cancer due to the identification of the BRCA1 and BRCA2 genes, mutations which may be associated with the development of breast cancer." (PMID 38473036, 2024). "Initial studies that examined the effect of a PRS on breast cancer risk in BRCA1 and BRCA2 carriers showed the absolute lifetime risk of breast cancer was around 10%–20% greater for carriers in the highest decile of the PRS distribution compared with the lowest." (PMID 39107016, 2024). "They observed that, in BRCA2-deficient breast cancer cells, the silencing of either AurkA or TPX2 causes a reduction in cell viability compared to BRCA2-proficient cells, suggesting that the survival of genomically unstable cancer cells depends on the AurkA/TPX2 signalling axis." (PMID 39195284, 2024). "This analysis revealed that some individuals with a pathogenic variant in PALB2 were diagnosed with breast cancer well before the age of 50 and had a similar risk to those with a BRCA2 variant before the age of 50 when, until recently, guidelines recommended beginning screening for everyone." (PMID 39669587, 2024). "A mutation in ATM: c.7969A>T was also found in the BRCA2 gene that is linked to breast carcinoma." (PMID 39281240, 2024). "Mutations in BRCA1 and BRCA2 make up around 15% of female breast cancer (FBC)." (PMID 38275884, 2024). "MPD shares the same risk factors as other breast carcinomas, including advanced age, obesity, alcohol consumption, familial genetic mutations including BRCA1 and BRCA2, prior chest radiation exposure, hormone replacement therapy, prolonged oral contraceptive use, and family history of breast cancer." (PMID 39188449, 2024). "If a BRCA1 or BRCA2 mutation is present, affected individuals develop breast cancer about 20 years earlier than women with sporadic cancer, with a cumulative lifetime risk of 60% on average for developing breast cancer and 16–55% for developing ovarian cancer." (PMID 36765786, 2023). "Germline BRCA2 mutation carriers frequently develop luminal-like breast cancers, but it remains unclear how BRCA2 mutations affect mammary epithelial subpopulations." (PMID 37626143, 2023). "A systematic literature review investigated whether physical activity levels during adolescence and young adulthood could decrease the lifetime risk of breast cancer among individuals carrying BRCA1 or BRCA2 germline variants." (PMID 37628558, 2023). "BRCA1 and BRCA2 mutations contribute to both breast cancer and ovarian cancer worldwide." (PMID 37312208, 2023).
breast cancer (continued). "However, certain risk factors such as family history, BRCA2 mutations, and hormonal imbalances can predispose some men to a higher risk of developing breast cancer." (PMID 38132204, 2023). "Similarly, for BRCA2 carriers, the highest cumulative risk was also breast cancer (58.3%), and the next two were prostate cancer (24.5%) and gastric cancer (19.3%)." (PMID 37476378, 2023). "Literature reports for women with an inherited BRCA1 mutation a lifetime risk for breast cancer of 65–80% and 37–62% lifetime risk for developing ovarian cancer, while it reports for BRCA2 mutation carriers a lifetime risk of 45–85% for breast cancer and 11–23% for ovarian cancer." (PMID 37365514, 2023). "However, gene screening is costly and BRCA1 or BRCA2 mutations cause only 5% of breast cancer, limiting applicability to the general population." (PMID 37018164, 2023). "For high-risk individuals with BRCA1 or BRCA2 mutations considering combined OCPs, genetics consultation should be considered to judge the competing impacts of increased breast cancer risk against individual needs and potential protective effects against ovarian cancer." (PMID 36980802, 2023). "In addition to the BRCA1 and BRCA2 genes, there are several other genes associated with an increased risk of breast cancer." (PMID 37958392, 2023). "An example can be seen in hereditary breast cancer whereby the demand for genetic testing to predict hereditary risks is increasing since the discovery of BRCA1 and BRCA2 genes as breast cancer susceptibility genes, which account for 5%–10% of hereditary breast cancer cases." (PMID 37168509, 2023). "If BRCA1-deficient breast cells are particularly sensitive to hormonal treatment, this could lead to a significantly higher risk of breast cancer compared with BRCA2 variant carriers associated with very early menopause and hormonal contraception use." (PMID 37340476, 2023). "Our findings suggest that BRCA1 c.5309G>T and BRCA2 c.1310_1313delAAGA mutations may have a strong founder and/or recurrent effect on breast cancer among the Northeastern Moroccan population." (PMID 37055759, 2023). "Phase 3 OlympiA clinical trial for Olaparib has demonstrated that patients with germline BRCA1 or BRCA2 pathogenic or likely pathogenic variants could obtain a benefit in early breast cancer." (PMID 37365643, 2023). "Data pertaining to the risk of seizures among women with advanced or metastatic breast cancer is limited, particularly when considering women who may harbor a mutation in the high risk BRCA1 and BRCA2 breast cancer predisposition genes." (PMID 36690978, 2023). "The A1108G mutation in canine BRCA2 was previously found in the canine mammary tumor sample." (PMID 36851449, 2023). "We identified patients with breast cancer harboring BRCA1 or BRCA2 mutations." (PMID 36905492, 2023). "Similarly, Berthorsson and colleagues observed higher levels of genetic aberrations and allelic imbalance at FRA3B in the BRCA2 mutated hereditary breast cancers than in the sporadic breast cancers." (PMID 37035242, 2023). "Accumulating evidence suggests that further clinical exploration of PARPi as monotherapy or combinations have shown benefit in patients with BRCA1 or BRCA2 mutation (gBRCAm)-associated breast cancer, as well as in breast cancer with homologous recombination repair (HRR) dysfunction." (PMID 36832085, 2023). "Furthermore, we did not evaluate other predictive factors, such as the effect of the type of surgery, family history of breast cancer, and the presence of a breast cancer gene 1/breast cancer gene 2 (BRCA1/BRCA2) gene mutation." (PMID 37182081, 2023). "Since the identification of BRCA1 and BRCA2 thirty years ago, many other genes have been proposed to be associated with moderate to high risk for breast cancer; however, limited and sometimes contradictory findings from studies have impeded a conclusive annotation." (PMID 37444426, 2023).
breast cancer (continued). "Additionally, in breast cancer with BRCA1 or BRCA2 gene mutations, the amplification percentage of CXCL1 gene is 3.85% (2/52)." (PMID 37108425, 2023). "Conversely, BRCA2-mutation-related breast cancers express HIF-1α less frequently." (PMID 36831687, 2023). "This hesitation may be heightened among BRCA1 and BRCA2 mutation carriers due to their differing baseline risks of breast cancer." (PMID 36765666, 2023). "So far, germ-line mutations within the BRCA2 gene, which is typically linked to breast cancer predisposition, have emerged as the most significant genetic events associated with an elevated PC risk, particularly notable with an 8.6-fold increase in men aged 65 or younger." (PMID 38054148, 2023). "To observe potential genetic interactions between BRCA1/2 and ALDH2 in a real‐world setting, we set out to recruit cases of BRCA1 and BRCA2 mutation carriers from breast cancer centers in Japan, and we determined ALDH2 genotypes using the previously established Taqman PCR assay." (PMID 36345163, 2023). "Furthermore, germline mutations in BRCA1 and BRCA2 have been linked to genetic predisposition to breast cancer." (PMID 38102637, 2023). "Genetic factors may also have a possible connection to MBC, and BRCA2 mutations appear to be the strongest risk factor for breast cancer in men with a lifetime risk of 7%, which is approximately 80 times more than the general population." (PMID 37152061, 2023). "However, IDC remains the most common type of breast cancer in those with mutations in the BRCA1 or BRCA2 genes." (PMID 37686673, 2023). "Moreover, BRCA1- and BRCA2-defective breast cancer cells, display an increased somatic mutational load specific of TLS polymerases." (PMID 36749784, 2023). "The most common cause of hereditary breast cancer are mutations in the BRCA1 or BRCA2 genes." (PMID 37108398, 2023). "BRCA1 and BRCA2 gene mutations are the most well-known genetic changes linked to breast cancer." (PMID 37886170, 2023). "While rare, high-penetrance mutations, such as BRCA1 and BRCA2, account for a minority of breast cancer cases, recent advancements in genomic sequencing technologies have opened new avenues for uncovering additional genetic modifiers that influence breast cancer risk." (PMID 38156855, 2023). "Mutations in BRCA1 and BRCA2 possess a higher risk of developing breast cancer in women." (PMID 36631481, 2023). "Similarly, the PARPi olaparib has been combined with the α-selective PI3K inhibitor alpelisib in a Phase 1b study of recurrent triple-negative or germline BRCA1 and BRCA2-mutated breast cancer." (PMID 37430137, 2023). "Women with pathogenic germline variants in the BRCA1 or BRCA2 gene have an increased lifetime risk of breast cancer (BC) and ovarian cancer (OC), compared to the general female population, with cancer occurring about twenty years earlier than the sporadic forms." (PMID 37845719, 2023). "Thus, in addition to BRCA1 and BRCA2, many other genes have been identified as susceptibility genes for breast cancer." (PMID 36896237, 2023). "In this large cohort of women carrying a pathogenic variant in BRCA1 or BRCA2, we found associations of height, BMI, and weight gain with breast cancer risk in pre- and postmenopausal women, which were generally consistent in direction and magnitude with those described in the general population." (PMID 37340476, 2023). "BRCA2 mutations have been linked with increased susceptibility to breast cancer in human studies." (PMID 36851449, 2023). "However, studies conducted in 2005 showed that breast cancer cells with mutations in the BRCA1 or BRCA2 genes are more susceptible to PARP-inhibition." (PMID 37509303, 2023). "Inherited mutations in BRCA1 and BRCA2 account for a small percentage of breast cancer cases." (PMID 37627192, 2023). "Women who carry the mutations of BRCA1 and BRCA2 have a higher risk of developing breast cancer." (PMID 37623253, 2023).
breast cancer (continued). "Notably, heterozygous mutations in FA genes, such as BRCA1/FANCS and BRCA2/FANCD1, increase the risk of cancer development, particularly in breast cancer." (PMID 37958890, 2023). "BRCA1 and BRCA2 mutation carriers represent 5–10% of females with breast cancer." (PMID 37987348, 2023). "For BRCA2-d, we observed a strong association with the number of deletions at sites of microhomology, with a median of 608 deletions per patient in BRCA2-d breast cancers versus 81 in BRCA2 WT breast cancers, in agreement with prior findings." (PMID 36883553, 2023). "Thus, finding out they were negative for BRCA reduced their perceived level of risk, despite being classified as elevated risk by WISDOM due to their PRS (which for some participants conferred the same five-year risk of breast cancer as a BRCA2 carrier)." (PMID 37311883, 2023). "Interestingly, the presence of pathogenetic BRCA2 mutations in the tumor of breast cancer patients before treatment at the level of a pronounced trend is associated with the effectiveness of NAC." (PMID 37628606, 2023). "Thus, we evaluated the association between vitamin D and/or calcium supplement use and breast cancer among women with a pathogenic variant (mutation) in BRCA1 or BRCA2." (PMID 37345127, 2023). "An alternative or complementary possible mechanism by which inherited BRCA2 mutations may enhance breast cancer risk is by causing defects in the differentiation or outgrowth of selected mammary epithelial subpopulations." (PMID 37626143, 2023). "Since she was at high risk for developing breast cancer as a carrier of a BRCA2 pathogenic variant, we performed core needle biopsy of the small breast mass with a 14-G needle after injecting local anesthetic subcutaneously and around the tumor under ultrasonographic guidance." (PMID 37957733, 2023). "For BRCA2 mutations, the lifetime risk of breast cancer is 45–69%." (PMID 36837501, 2023). "Moreover, this PML risk panel test was positive for 10.9% of PML cases in our study, which is higher than the presence of BRCA1 and BRCA2 variants in breast cancer patients (2.8 and 2.7%, respectively)." (PMID 36588876, 2022). "Our study is an advancement over previous ones due to the incorporation of variables from up-to-date peer-reviewed studies considering the type of pathogenic variant (BRCA1 or BRCA2), age at primary breast cancer diagnosis, breast cancer subtype and stage, status of systemic treatment received." (PMID 36580360, 2022). "These variants are mostly prevalent in breast cancer genes BRCA2, CHEK2 and ATM." (PMID 36581909, 2022). "BRCA2 mutation occurred frequently in breast cancer 62, ovarian cancer 63, and prostate cancer." (PMID 36147475, 2022). "Indeed, BRCA1 and BRCA2 mutation carriers have risks of 57% and 49%, respectively, for developing breast cancer." (PMID 36140723, 2022). "The mutation of BRCA2 gene mutations account for around 20-40% of familial breast cancer cases." (PMID 36268271, 2022). "Moreover, in families with BRCA mutations, there is an increased risk of male breast cancer, although the risk appears to be greater with inherited BRCA2 mutations than with inherited BRCA1 mutations." (PMID 35885460, 2022). "Somatic mutations in BRCA1/BRCA2 have been shown to occur in 2.5% of all sporadic breast cancers." (PMID 35884530, 2022). "However, emerging evidence suggests that a subset of BRCA1/BRCA2 wild-type breast cancer patients can also have deficiencies in homologous recombination." (PMID 35884530, 2022). "All but one BRCA2 mutation carrier with breast cancer were female." (PMID 36344544, 2022). "BRCA1 and BRCA2 mutations account for approximately 5% of all breast cancer cases." (PMID 35743744, 2022).